VWF (von Willebrand factor)
Diseases named in the same sentence as VWF in open-access papers (continued):
Sharing a sentence is not in itself a finding about the gene and the disease.
preeclampsia (14 papers, 2013 to 2025). Preeclampsia is a hypertensive disorder of pregnancy that is characterized by new-onset hypertension with proteinuria presenting after 20 weeks of gestation, and depending on mild or severe forms may initially present with severe headache, visual disturbances, and hyperreflexia. "In TTP, there is a typically severe ADAMTS13 deficiency, leading to excessive von Willebrand factor activity and microthrombi formation, while in preeclampsia, ADAMTS13 activity is usually lower but within normal range." (PMID 38673014, 2024). "A study investigating the maternal proteome in preeclampsia via LC–MS/MS approaches reported on 17 differentially expressed proteins in the serum, from which our study also identified VWF, PAPPA, FCN3, and ITIH1 as candidates associated with the mode of conception." (PMID 40974471, 2025). "Thus, in the case of preeclampsia associated with bleeding symptoms, VWF deficiency should be taken into account." (PMID 24385790, 2013). "On the other hand, VWF deficiency could be a risk factor for preeclampsia." (PMID 24385790, 2013). "Preeclampsia is associated with an early decline of ADAMTS13 activity independently of VWF concentration, thus resulting in an increase in circulating VWF with high placental microthrombotic risk." (PMID 40362344, 2025). "The increase in NE expression is proportional to endothelial damage which is mediated by the overexpression of vWF, which correlates to the severity of preeclampsia." (PMID 39301340, 2024). "Dysregulation of the balance between vWF and ADAMTS13 has been implicated in endothelial dysfunction and thrombotic microangiopathy, which are central features of preeclampsia." (PMID 38673014, 2024). "Recently, one study proposed that the ADAMTS13-von Willebrand factor pathway play a key role in normal pregnancy and pathogenesis of preeclampsia." (PMID 33549121, 2021). "HELLP, a serious complication of pregnancy-associated preeclampsia, is characterized by impaired ADAMTS-13 activity, excessive release of vWF multimers, the production of activated vWF, and subsequent microvascular platelet thrombosis." (PMID 32241296, 2020). "Furthermore, the FVIII:VWF ratio was also reported to be more dramatically decreased in pregnancies complicated by preeclampsia, and has even been proposed as a prognosticator of complicated pregnancies." (PMID 25409031, 2014). "Thus, the reduced enzyme activity could promote the formation of large vWF polymers on endothelial cells and platelets and thereby increase vascular prothrombotic activity in preeclampsia." (PMID 40671815, 2025).
acute respiratory distress syndrome (13 papers, 2009 to 2025). Progressive and life-threatening pulmonary distress in the absence of an underlying pulmonary condition, usually following major trauma or surgery. "Interestingly, in patients with acute lung injury/acute respiratory distress syndrome, higher angiopoietin-2, as well as vWF levels, were associated with pulmonary permeability oedema." (PMID 38257821, 2024). "VWF has been associated with inflammatory situations, such as the diagnosis of acute respiratory distress syndrome (ARDS), in which increased levels are associated with bad outcomes, long mechanical ventilation times, and mortality." (PMID 40700333, 2025). "These contain the Von Willebrand Factor responsible for micro-clotting and angiopoietin-2 which increases vascular permeability and plays a key role in the Acute Respiratory Distress Syndrome." (PMID 34867791, 2021). "The role of vWF is best known in terms of haemostasis, but recently it has become evident that circulating levels of vWF can be markers for acute respiratory distress syndrome and COPD." (PMID 25133674, 2014).
cerebral malaria (13 papers, 2009 to 2025). A sequestration of Plasmodium falciparum in the brain, which can cause coma and/or seizures. "The recovery of cerebral malaria patients was associated with a significant decline in both VWF and propeptide levels towards normal values in healthy Malawian controls." (PMID 22125593, 2011). "Indeed, recent works have linked the platelet-mediated clumping of infected erythrocytes in microvasculature during cerebral malaria with increased level of VWF in plasma caused by mutations in ADAMTS13 genes." (PMID 34868193, 2021). "A novel aspect of this study is the assessment of plasma VWF and propeptide levels in cerebral malaria cases confirmed on the basis of malarial retinopathy." (PMID 22125593, 2011). "A subset of cerebral malaria children (n = 7) was studied prospectively to relate plasma VWF and propeptide levels at the time of admission to plasma levels 48 hours and 30 days after the start of treatment." (PMID 22125593, 2011). "We have studied the effect of Plasmodium falciparum infection on the endothelial cell activation marker, the multimeric adhesive protein von Willebrand factor (VWF) in a cohort of patients with severe infection or cerebral malaria." (PMID 19300493, 2009). "Given that mice without VWF had a higher survival rate in cases of cerebral malaria, experimental models suggest that vWF plays a pathogenic function." (PMID 41002937, 2025). "However, vWF levels were significantly higher in cerebral malaria compared to severe malarial anemia, and they increased with the severity of acute kidney failure." (PMID 40283058, 2025). "Furthermore, compared with WT controls, VWF knockout mice tend to exhibit obviously alleviated BBB permeability in a model of cerebral malaria, hypoxia, and seizures." (PMID 32075652, 2020). "Notably, in the plasma of cerebral malaria patients the release of increased levels of vWF has been reported after Plasmodium falciparum infection." (PMID 27224245, 2016). "To determine whether VWF and propeptide are prognostic markers for death in confidently-diagnosed paediatric cerebral malaria, we measured plasma protein levels in retinopathy positive children who recovered and those who died." (PMID 22125593, 2011). "We have previously shown that patients with severe infection or fulminant cerebral malaria have significantly increased circulatory levels of the adhesive glycoprotein von Willebrand factor (VWF) and its propeptide, both of which are indices of endothelial cell activation." (PMID 19300493, 2009). "Recent studies reported increased levels of von Willebrand factor (VWF) and reduced activity of VWF-cleaving protease, ADAMTS13 (a disintegrin and metalloproteinase with a thrombospondin type 1 motif, member 13), in patients with cerebral malaria." (PMID 22168261, 2011). "Platelet count did not correlate with either VWF or VWF propeptide in children with retinopathy positive cerebral malaria (rho = −0.165, p = 0.160 and rho = −0.074; P = 0.533, respectively)." (PMID 22125593, 2011). "The surprising result from our study comes from the comparison of VWF and propeptide levels in cases defined clinically as cerebral malaria but divided into retinopathy positive and negative." (PMID 22125593, 2011). "VWF and propeptide plasma concentrations were compared between cerebral malaria children with retinopathy and those without retinopathy." (PMID 22125593, 2011). "The observation that plasma VWF and propeptide levels were not significantly different between children who died and those who recovered suggests that these proteins are not prognostic markers of death in cerebral malaria." (PMID 22125593, 2011). "It is not possible to say whether VWF and VWF propeptide are more markedly elevated specifically in retinopathy positive cerebral malaria than other central nervous system (CNS) severe illnesses in the presence of malaria infection." (PMID 22125593, 2011).
hepatocellular carcinoma (13 papers, 2017 to 2025). A malignant tumor that arises from hepatocytes. "Prospective multicenter studies have found that serum VWF levels can influence HCC recurrence, and higher VWF is associated with early recurrence of hepatocellular carcinoma." (PMID 35847002, 2022). "In 2019, Takaya and colleagues reported that an imbalance of ADAMTS13 with its substrate, von Willebrand factor, could be used as a detection marker for diagnosis of hepatocellular carcinoma." (PMID 35011462, 2021). "Tumor small extracellular vesicle (sEV)‐derived von Willibrand factor (vWF) induces a positive feedback loop between tumor and endothelial cells to promote angiogenesis and metastasis in hepatocellular carcinoma (HCC)." (PMID 37387563, 2023). "Furthermore, Western blotting, immunohistochemical analysis of liver biopsies and ELISA from plasma samples revealed a correlation between VWF expression and hepatocellular carcinoma cell (HCC) clinicopathologic staging." (PMID 34572000, 2021). "The discrepant results obtained from the TCGA and GEO databases regarding VWF and ADAMTS13 highlight the imbalance between VWF and ADAMTS13 in hepatocellular carcinoma (HCC)." (PMID 40699668, 2025).
hyperthyroidism (13 papers, 2008 to 2024). Overactivity of the thyroid gland resulting in overproduction of thyroid hormone and increased metabolic rate. "However, another MR study regarding the effects of thyroid function on coagulation and fibrinolysis revealed that genetically predicted hyperthyroidism was associated with increased VWF and FVIII, resulting in a hypercoagulable and hypofibrinolytic state." (PMID 39054435, 2024). "Hyperthyroidism is associated with an increase in vWF activity levels which may consecutively lead to increased cardiovascular risk." (PMID 36064879, 2023). "The hyperthyroidism group had significantly higher values for vWF, TM, NO, ET-1, and P-selectin in serum and a higher number of EPCs in whole blood compared with the control group, similar to the LOX-1 expression in abdominal aorta." (PMID 32332761, 2020). "The hyperthyroidism low iodine group had significantly higher values for vWF, ET-1, and P-selectin in serum and a higher number of EPCs in whole blood compared with those of the control group, as was the case for LOX-1 expression in the abdominal aorta." (PMID 32332761, 2020). "In our study, serum vWF level was higher in the groups with both subclinical hyperthyroidism and overt hyperthyroidism, but the difference was significant only between the OH and control groups." (PMID 24367378, 2013). "In particular, the importance of thyroid hormone levels on coagulative function has been demonstrated by the presence of significantly increased levels of vWF, fibrinogen, and D-dimer, even in patients with subclinical hyperthyroidism, when compared to euthyroid patients." (PMID 38003871, 2023). "Compared to the control group, the serum levels of vWF in the hyperthyroidism model group (457.75 ± 29.06 ng/L), the H + low iodine group (412.77 ± 28.74 ng/L), the high iodine group (495.36 ± 39.58 ng/L) and the endothelial injury group (402.84 ± 31.61 ng/L) were significantly higher (P < 0.05)." (PMID 32332761, 2020). "Moreover, Ordookhani and Burman reported that vWF is increased in adults with overt hyperthyroidism, where thyroid hormone excess stimulates thyroid receptors on endothelial cell and increase vWF level by influencing vVF synthesis through altering the expression of their genes." (PMID 37022495, 2023). "Several studies indicate that patients with hyperthyroidism in comparison to euthyroid controls show a significant increase in the levels of fibrinogen, FVIII, FIX, and vWF." (PMID 38541980, 2024). "Patients with hyperthyroidism had significantly higher levels of FVIII and vWF compared to those patients with hypothyroidism and euthyroid individuals." (PMID 38541980, 2024).
type 1 von Willebrand disease (13 papers, 2012 to 2026). "Rather, there is an age-dependent evolving phenotype in individuals with partial quantitative VWF deficiency, and Low VWF is a subgroup within heterogeneous type 1 VWD." (PMID 39265913, 2024). "In conclusion, we have shown that genetic variation in STX2 is associated with VWF:Ag levels in patients previously diagnosed with type 1 VWD." (PMID 22792389, 2012). "Type 1 VWD is characterized by a mild presentation associated with reduced VWF levels." (PMID 41322438, 2025). "Genetic variation in STX2 is associated with VWF:Ag levels in patients diagnosed with type 1 VWD." (PMID 22792389, 2012). "Interestingly, the frequency of the minor allele of rs7978987 that was significantly associated with higher VWF:Ag levels, was much lower in our type 1 VWD patients (MAF = 0.29) than reported by dbSNP (MAF = 0.38) and the CHARGE consortium (MAF = 0.35)." (PMID 22792389, 2012). "In approximately 30% of type 1 VWD patients, plasma VWF levels increased into the 30 to 50 IU/dL range over time (WiN partially corrected)." (PMID 39265913, 2024). "Patients with significant personal bleeding and VWF levels persistently in the 30 to 50 IU/dL range are registered with a type 1 VWD diagnosis." (PMID 39265913, 2024). "A variety of bleeding diseases are known in dogs including von Willebrand disease type I. This genetic disorder affects the von Willebrand factor in plasma which is important for blood clotting." (PMID 31131110, 2019). "In type 1 VWD patients, who have reduced but functionally normal VWF molecules, VWF levels are highly variable." (PMID 22792389, 2012). "We are the first to describe the association between genetic variation in SNARE protein genes and VWF:Ag levels and VWF:CB in patients previously diagnosed with type 1 VWD." (PMID 22792389, 2012). "In the current study we have shown that genetic variation in STX2 and to a lesser extent in STXBP5 contributes to VWF:Ag levels in patients diagnosed with type 1 VWD." (PMID 22792389, 2012). "Dysfunction of the WPB machinery is a likely contributor to the variation in VWF:Ag levels in type 1 VWD patients." (PMID 22792389, 2012). "We assessed the relationship between genetic variations in STXBP5 and STX2, VWF levels, and bleeding phenotype in type 1 VWD patients." (PMID 22792389, 2012). "In today's clinical practice diagnosis of type 1 VWD is difficult, because of the high variability in VWF plasma levels and the incomplete penetrance of the phenotype." (PMID 22792389, 2012). "For these reasons it is sometimes hard to distinguish between physiologically low VWF levels and low VWF levels because of type 1 VWD." (PMID 22792389, 2012). "Moreover, in a further 23% of type 1 VWD patients, plasma VWF:Ag levels increased into the normal range (>50 IU/dL) with progressive aging (WiN normalized)." (PMID 39265913, 2024). "However, in support of that decision, recent data have demonstrated that individuals with partial quantitative VWF deficiency exhibit an age-dependent evolving phenotype and confirmed that Low VWF represents a subgroup within heterogeneous type 1 VWD." (PMID 39265913, 2024). "Since VWF is a continuous trait, categorizing it into discrete diagnostic groups is challenging and does not fully represent the complexity underlying type 1 VWD biology." (PMID 39265913, 2024). "Thus, the guidelines proposed that patients with plasma VWF:Ag levels < 30 IU/dL and bleeding should be diagnosed with type 1 VWD." (PMID 39265913, 2024). "Our findings may partly explain the variable VWF levels and bleeding phenotype in type 1 VWD patients." (PMID 22792389, 2012). "Our findings may explain part of the variation in VWF levels and bleedings symptoms in patients with type 1 VWD." (PMID 22792389, 2012). "Therefore, we aimed to assess the relationship between genetic variation in STXBP5 and STX2, VWF:Ag levels, and the bleeding phenotype in patients previously diagnosed with type 1 VWD." (PMID 22792389, 2012).
type 1 von Willebrand disease (continued). "Three large studies in Europe, the United Kingdom and Canada showed that only 65% of the type 1 VWD patients have candidate mutations, meaning that 35% have no apparent VWF mutations." (PMID 22792389, 2012). "In addition, genetic variation in STXBP5 and STX2 may, by regulating VWF:Ag levels, influence the incomplete penetrance and the variable clinical presentation of type 1 VWD." (PMID 22792389, 2012). "It is noteworthy that DDAVP’s effectiveness is predominantly in type 1 vWD, with limited to no efficacy in type 3 and certain subtypes of type 2 vWD, where the vWF protein is either absent or dysfunctional, respectively." (PMID 40572775, 2025). "In line with the guideline recommendations, patients with VWF levels < 30 IU/dL (red) are diagnosed as type 1 VWD, and individuals with VWF levels > 50 IU/dL without any bleeding symptoms (green) are considered healthy." (PMID 39265913, 2024). "In 158 patients diagnosed with type 1 VWD according to the current ISTH guidelines, we genotyped three tagging-SNPs in STXBP5 and STX2 and analyzed their relationship with VWF:Ag levels and the severity of the bleeding phenotype, as assessed by the Tosetto bleeding score." (PMID 22792389, 2012). "Consequently, healthy subjects with plasma VWF:Ag levels of 30 to 50 IU/dL without a significant bleeding phenotype should NOT be given a type 1 VWD diagnosis nor labeled “Low VWF,” irrespective of the reason for initial VWF measurement in these individuals." (PMID 39265913, 2024). "Labeling this entire cohort with a type 1 VWD (rather than Low VWF) diagnosis may provide an important opportunity to reduce healthcare access barriers in the United States and decrease morbidity associated with delays to first diagnosis." (PMID 39265913, 2024). "Furthermore, as blood group O corresponds with lower VWF:Ag levels, patients diagnosed with type 1 VWD more frequently have blood group O than non-O." (PMID 22792389, 2012).
Cerebral ischemia (12 papers, 2010 to 2025). Restriction of arterial blood supply to the brain associated with insufficient oxygenation to support the metabolic requirements of the tissue. "In mouse models of cerebral ischemia/reperfusion injury, VWF deficient mice indeed showed less thrombosis in the cerebral microvasculature, as shown by reduced intracerebral fibrin(ogen) deposition in the affected brain tissue of these animals compared to wild-type mice." (PMID 31921147, 2019). "The von Willebrand factor (VWF) A1 domain plays a crucial role in mediating the inflammatory response during cerebral ischemia/reperfusion by recruiting inflammatory monocytes, neutrophils, and T cells." (PMID 40356948, 2025). "Dihydroartemisinin (DHA) has been found to inhibit the expression of von Willebrand factor (VWF), a marker of endothelial cell injury, but its mechanism in cerebral ischemia/reperfusion (I/R) injury remains obscure." (PMID 37415610, 2023). "Together, these studies highlight the pathophysiological involvement of VWF and GPIbα in cerebral ischemia/reperfusion injury, which can be counterbalanced by blocking the VWF-GPIbα interaction or by reducing the activity of VWF via ADAMTS13." (PMID 31921147, 2019). "In parallel with these studies on VWF, similar research demonstrated that also GPIbα is an important mediator of cerebral ischemia/reperfusion injury." (PMID 31921147, 2019). "The PACAP38 was strongly coexpressed with Neu-N, GFAP, and vWF in ischemic areas, suggesting brain ischemia upregulated PACAP38 in neurons, glia, and endothelial cells." (PMID 25523790, 2015). "Additionally, targeting NETs protected mice from tMCAO-induced cerebral ischemia, possibly by mediating von Willebrand factor and plasminogen activator inhibitor-1 in the blood and thrombi." (PMID 37508923, 2023). "Furthermore, in a canine thromboembolic brain ischemia model, transplanted CB-MSCs had differentiated into neurons and astrocytes and were observed in and around endothelial cells that were positive for von Willebrand factor (vWF)." (PMID 20957109, 2010).